TERT (telomerase reverse transcriptase)
Diseases named in the same sentence as TERT in open-access papers (continued):
Sharing a sentence is not in itself a finding about the gene and the disease.
myocardial infarction (9 papers, 2013 to 2023). Gross necrosis of the myocardium, as a result of interruption of the blood supply to the area, as in coronary thrombosis. "Acute overexpression of TERT increases survival and decreases infarct size in a mouse model of myocardial infarct, while decreased telomerase activity predisposes to mitochondrial defects and heart failure." (PMID 31001540, 2019). "Following this concept, a recent study used an adeno-associated virus of serotype 9 (AAV9) for TERT re-expression specifically in cardiac myocytes to determine the therapeutic potential in a mouse model of myocardial infarction induced by coronary artery ligation." (PMID 27322328, 2016). "Intravenous injection of this vector into mouse models of myocardial infarction showed that mice with the vector expressing TERT had less damage to the cardiac indices of both structure and function, decreased mortality and improved biomarkers." (PMID 37008065, 2023). "Haendeler’s group has recently shown that TA-65 is a mitochondrial rather than nuclear telomerase activator, which depends on the presence of TERT, improving the outcome of mice after experimental myocardial infarction." (PMID 37086366, 2023). "In a preclinical mouse model, improved ventricular function and the reduction in infarct scars after acute myocardial infarction was achieved through TERT gene therapy." (PMID 36552277, 2022). "This clear demonstration of protective functions of mitochondrial TERT in myocardial infarction suggests that a therapeutic increase in mitochondrial TERT would be beneficial in cardiovascular diseases." (PMID 34944035, 2021). "We have recently shown that transplantation of AT‐MSCs overexpressing MYOCD and TERT induced an increase in the pool of cardiac resident CSCs in the infarcted cardiac tissue in a murine model of acute myocardial infarction." (PMID 33949765, 2021). "In a clinical study, TERT up‐regulation facilitated growth differentiation factor 11 (GDF11)‐mediated restoration of VEGFR2+/CD133+ cells isolated from older adult patients who had suffered myocardial infarctions via eNOS and SMAD 2/3 signalling." (PMID 37041671, 2023). "Cardiac specific induced TERT overexpression in a myocardial infarction mouse model has been shown to attenuate cardiac dilation, improve ventricular function and decrease infarct size in left anterior descending artery ligation, and decrease apoptosis in vivo and in cultured cardiomyocytes." (PMID 31001540, 2019). "Taking these results regarding the role of Telomerase and TERT in the heart together, it seems to be reasonable to develop new therapeutic strategies based on Telomerase activation to improve the outcome after myocardial infarction and to potentially treat heart failure." (PMID 27322328, 2016).
nasopharyngeal carcinoma (9 papers, 2010 to 2025). A carcinoma arising from the nasopharyngeal epithelium. "We examined whether polymorphisms in the TERT-CLPTM1L locus were related to the risk of developing nasopharyngeal carcinoma (NPC) among Chinese populations." (PMID 26621837, 2016). "Increases in human telomerase reverse transcriptase (TERT) expression and telomerase activity are frequently seen in nasopharyngeal carcinoma (NPC)." (PMID 21929825, 2011). "Moreover, LMP1 has been shown to modulate telomerase activity at a post-transcriptional level by inducing the direct binding of TERT to NF-κB p65 and nuclear translocation of TERT in nasopharyngeal carcinoma cells." (PMID 36358677, 2022). "We further found that Par-4 can interact with TERT in a yeast two-hybrid system, and other studies have indicated that the interaction between Par-4 and TERT may inhibit TERT in the cytoplasm of nasopharyngeal carcinoma cells, leading to apoptosis." (PMID 30186877, 2018). "In human nasopharyngeal carcinoma (NPC), for instance, TERT is mainly found in the cytoplasm of tumor cells, while in lymph node metastases, it is predominantly localized in the nucleus." (PMID 39871386, 2025). "In particular, it has been demonstrated that LMP-1 activates TERT in nasopharyngeal carcinoma cells through the AKT pathway: in established LCLs, LMP-1 activates TERT at transcriptional level via the NF-κB and MAPK/ERK1/2 pathways." (PMID 29643934, 2018). "However, at present, the biological significance of the TERT subcellular location in the process of in vivo lymphatic metastasis of nasopharyngeal carcinoma (NPC) remains unclear." (PMID 25435972, 2015).
thalassemia (9 papers, 2018 to 2024). An inherited blood disorder characterized by a decreased synthesis of one of the polypeptide chains that form hemoglobin. "With rare exceptions, TERT promoter mutations, which lead to an increase in telomerase expression, and inactivating mutations in the thalassemia/mental retardation syndrome X-linked (ATRX) gene, are mutually exclusive, and are associated with different molecular tumor subclasses." (PMID 34558656, 2022). "These include either ATRX (a-thalassemia/mental retardation syndrome X linked) mutations, which can lead to the ALT (alternative lengthening of telomeres) phenotype, or TERT overexpression, as a result of TERT gene rearrangements." (PMID 33808071, 2021).
type 2 diabetes (9 papers, 2017 to 2025). "Therefore, we further investigated the association between Par-4 and TERT in islet β cell apoptosis induced by high-glucose/palmitate levels, which mimics type 2 diabetes." (PMID 30186877, 2018). "The prevalence of type 2 diabetes was decreased in homozygotes of the rs2736100 SNP of the TERT gene." (PMID 36359275, 2022). "A previous study demonstrated that the incidence of type 2 diabetes was increased in carriers of the CC SNP (rs2853669) of the TERT gene." (PMID 36359275, 2022). "This work elucidates the specific mechanism of binding between TERT and Par-4 that is involved in islet β cell apoptosis and provides a novel target for gene therapy in type 2 diabetes and other age-related diseases." (PMID 30186877, 2018). "Our findings suggest that the Par-4/TERT-Akt pathway plays an important role in the apoptosis of islet β cells in type 2 diabetes." (PMID 30186877, 2018). "Hence, we detected the concentrations of Par-4 and TERT in newly diagnosed type 2 diabetes patients." (PMID 30186877, 2018). "Indeed, several recent studies indicate an important role for cis-regulatory mutations in disease, not only in cancer (e.g., TERT, TAL1), but also in complex diseases (e.g., type II diabetes FTO locus, Parkinson’s disease) and in familial disorders (e.g., preaxial polydactyly)." (PMID 28854983, 2017). "There were significant differences in fasting blood glucose (FBG), HbA1c, C-peptide, HOMA-β, Par-4, TERT, TG, and HDL-C (P < 0.05) between the type 2 diabetes group and the control group." (PMID 30186877, 2018). "Therefore, we herein report for the first time a novel role of Par-4 interaction with TERT, followed by nuclear translocation to induce islet β cell apoptosis, and we reveal the relationship between Par-4 and Akt signalling in the apoptosis of islet β cells in type 2 diabetes." (PMID 30186877, 2018). "There are no available reports on the roles of Par-4 and TERT in islet β cell apoptosis in type 2 diabetes." (PMID 30186877, 2018). "Although these results did not directly reflect the β cell concentrations of Par-4 and TERT, they indicated that Par-4 and TERT may show some relationship with islet β cell dysfunction in type 2 diabetes." (PMID 30186877, 2018). "Whether Par-4 and TERT are involved in islet beta cell dysfunction in the course of type 2 diabetes has not previously been reported." (PMID 30186877, 2018).
atherosclerosis (8 papers, 2008 to 2024). A disease characterized by the build-up of fatty material and calcium deposition in the arterial wall resulting in partial or complete occlusion of the arterial lumen. "Although reductions in telomerase reverse transcriptase (TERT) expression levels and telomerase activity have been implicated in atherosclerosis, definitive mechanisms are yet to be elucidated." (PMID 39120300, 2024). "To clarify the effect of TERT on atherosclerosis-associated phenotypes in OA-treated VSMCs, we transfected TERT siRNA into VSMCs." (PMID 39223261, 2024). "We also found that TERT knockdown increased atherosclerosis-associated phenotypes, as indicated by increased TNF-α and ADRP protein levels and increased cellular lipid accumulation, as determined using the BODIPY probe, compared with those in the con siRNA+OA+Met group." (PMID 39223261, 2024). "Based on our findings, we propose that Met has anti-aging and anti-atherosclerosis effects through the AMPK/PGC-1α/TERT pathway." (PMID 39223261, 2024). "The switching phenotypes of senescent VSMCs, which were positively correlated with the pathogenesis of atherosclerosis, showed greater collagen I expression in the TERT siRNA+OA+Met group than in the con siRNA+OA+Met group." (PMID 39223261, 2024). "Additionally, CAT is reported to reduce mitochondrial damage and attenuate atherosclerosis by activating the peroxisome proliferator-activated receptor-γ coactivator-1/telomerase reverse transcriptase (PGC-1/TERT) pathway." (PMID 33510841, 2021). "Given the effect of statins on telomerase activity and the role of TERT in proliferation of CD4+ cells suggests that TERT might also have a function in the generation of an anti-inflammatory T-cell response in atherosclerosis via upregulation of Treg-numbers." (PMID 27322328, 2016). "Mechanistically, the phosphorylation of AMPK and PGC-1α by metformin not only enhanced telomere function but also increased the protein level of TERT, whereas TERT knockdown accelerated the development of atherosclerosis and senescent phenotypes in OA-treated VSMCs regardless of metformin treatment." (PMID 39223261, 2024).
coronary artery disease (8 papers, 2013 to 2022). "However, little study directly focused on the association between TERT gene polymorphisms and risk of coronary heart disease (CHD)." (PMID 28978050, 2017). "Furthermore, genome-wide association studies of adult leukocyte TL (LTL) identified 7 single-nucleotide variations (ACYP2, NAF1, OBFC1, RTEL1, TERC, TERT, ZNF208) linked with LTL that mutually project towards an increased risk for coronary artery disease." (PMID 35930283, 2022). "Moreover, locus cg12324353 within TERT was recently reported to be related to coronary artery disease." (PMID 27323854, 2016).
myeloproliferative neoplasm (8 papers, 2014 to 2024). A clonal hematopoietic stem cell disorder, characterized by proliferation in the bone marrow of one or more of the myeloid (i.e., granulocytic, erythroid, megakaryocytic, and mast cell) lineages. "A recent meta-analysis confirmed that the TERT rs2736100 polymorphism is associated with increased overall cancer risk, including solid cancers, myeloproliferative neoplasms, and acute myeloid leukemia." (PMID 29641446, 2018). "The telomerase reverse transcriptase (TERT) gene rs2736100_C allele has recently been shown to be associated with an increased risk for myeloproliferative neoplasms (MPNs) among Caucasians." (PMID 27561898, 2016). "The C allele of the rs2736100 single nucleotide polymorphism located in the second intron of the TERT gene has recently been identified as a susceptibility factor for myeloproliferative neoplasms (MPN) in the Icelandic population." (PMID 25196853, 2014). "Germline variations at JAK2, TERT, HBS1L-MYB and MECOM have been found to associate with myeloproliferative neoplasms (MPNs) in European populations." (PMID 29100304, 2017).
myxoid liposarcoma (8 papers, 2014 to 2025). A liposarcoma characterized by the presence of round non-lipogenic primitive mesenchymal cells and small signet ring lipoblasts within a myxoid stoma with a branching vascular pattern. "Correlation of the TERT promoter variant with clinicopathologic parameters in patients with myxoid liposarcoma." (PMID 40489430, 2025). "The high frequency of hotspot mutations (C228T or C250T) in the promoter region of telomerase reverse transcriptase TERT that encodes the TERT protein has also been found in myxoid liposarcoma." (PMID 35847001, 2022). "By far the far highest frequency of TERT promoter mutations was found in myxoid liposarcoma (MLS) (4 out of 9 cases studied, i.e., 44%)." (PMID 29463038, 2018).
oligodendroglial tumor (8 papers, 2014 to 2022). Oligodendrogliomas are cerebral tumors that are differentiated from other gliomas on the basis of their unique genetic characteristics and better response to chemotherapy. "The group with mutations in both IDH and TERT consisted of only oligodendroglial tumors (6/6, 100%)." (PMID 30076584, 2018). "TERT promoter mutations were observed in 84 of 138 tumors (60.9%), including 7 oligodendroglial tumors (7/8, 87.5%) and 69 GB (69/113, 61.1%) (Online Resource 3)." (PMID 30076584, 2018). "However, in oligodendroglial tumors, TERT promoter and IDH mutations occurred together (OR = 26.25; 95% CI 2.46 – 250.20; P = 0.001)." (PMID 25797251, 2015). "However, in oligodendroglial tumors, TERT promoter and IDH mutations occurred together (p<0.001)." (PMID 34558656, 2022). "In line with the previous studies, TERT expression was confirmed in the nuclei of oligodendroglial tumors and IDH-wildtype GBM which possess either of two hotspot mutations in the promoter regions of TERT." (PMID 29693015, 2018).
phyllodes tumor (8 papers, 2017 to 2025). A benign, borderline, or malignant fibroepithelial neoplasm arising from the breast and rarely the prostate gland. "On the other hand, TERT promoter mutations were rare in FAs and, according to literature, are progressively more frequent in benign, borderline, and malignant categories of phyllodes tumors." (PMID 38055384, 2023). "TERT promoter hotspot mutations have been documented in phyllodes tumors, and found to be more frequent in borderline and malignant lesions." (PMID 29043292, 2017). "Furthermore, while the differentiation between phyllodes tumors and fibroadenomas often presents clinical challenges, TERT promoter mutations have been established as particularly useful diagnostic markers." (PMID 39597083, 2024). "A recurrent clonal hotspot mutation in the TERT promoter (-124 C>T) was observed in 52% and TERT gene amplification in 4% of phyllodes tumors." (PMID 39996866, 2025). "The authors concluded that TERT alterations might drive the progression of phyllodes tumors and could aid in the differential diagnosis between phyllodes tumors and fibroadenomas." (PMID 39996866, 2025).
prostate (8 papers, 2016 to 2025). "In this study, we used two large-scale population datasets from European and Chinese ancestries to comprehensively estimate the association of TERT loci polymorphisms with prostate tumorigenesis and severity." (PMID 37174115, 2023). "For example, a chromosomal rearrangement resulting in translocation of the IRX2 promoter to the TERT locus has been found to drive TERT expression in clear cell sarcoma of kidney." (PMID 28264499, 2017). "The lowest TERT expression was found in breast (BRCA), pancreas (PAAD) and prostate (PRAD) cancer." (PMID 31888467, 2019).
uveal melanoma (8 papers, 2017 to 2024). A melanoma derived from melanocytes of the uveal tract. "In contrast for uveal melanoma TERT promoter mutations are extremely rare." (PMID 35494035, 2022). "Similar to TERT promoter mutations, ATRX loss is very rare in uveal melanoma, which is another ocular melanoma." (PMID 37629169, 2023). "Another remarkable observation in our study is that in WT TERT-expressing uveal melanoma cell lines, the methylation of the whole TERTp region is close to 100% with a significantly higher chromatin accessibility compared to TERTp-mutated cell lines." (PMID 32267900, 2020). "We also detected nucleotide transitions resulting in gene activation in NRAS (Q61K, Q61R), in the promoter region of TERT (chr5:1295250 G > A), and in GNA11 (R183C), the latter being frequent in uveal melanoma and primary meningeal melanocytic tumors." (PMID 33578810, 2021).
viral infection (8 papers, 2013 to 2025). "Because MCV is frequently detected in MCC and implicated in the disease pathogenesis, we are interested in a potential association between the virus infection and TERT promoter mutation or gene amplification." (PMID 25301727, 2014). "Gene transfer techniques include liposome transfection, electrotransfection, and viral infection, with lentivirus being employed in our study for TERT gene transfer into UCMSCs, followed by puromycin screening." (PMID 39056743, 2024). "Uninfected primary human hepatocytes (PHH) did not express TERT or endogenous telomerase activity until after viral infection and then new TERT protein and TRAP activity were observed concomitant with the rise of HCV RNA." (PMID 28056029, 2017). "After viral infection, TERT staining increased and localized prominently to perinuclear granules." (PMID 28056029, 2017). "We recently summarized the non-canonical functions of TERT in viral infections and cancer." (PMID 40025596, 2025).
anaplastic astrocytoma (7 papers, 2016 to 2024). "In accordance, we found a low percentage of pilocytic, diffuse, and anaplastic astrocytomas presenting mutations in the TERT promoter gene." (PMID 27172220, 2016). "Among GBMs, two cases were originally diagnosed as anaplastic astrocytoma according to WHO 2016 classification; however, CGPT revealed that they harbored EGFR amplification and TERT promoter mutation, and they were reclassified as GBM based on WHO 2021 classification." (PMID 35626060, 2022). "A correlation between alterations of these genes and poor prognosis has been observed for RB1 in non‐small‐cell lung cancers 37 and anaplastic astrocytoma 38, and increased mRNA expression of TERT was previously reported as a poor prognostic marker in breast 39 and lung 40 cancers." (PMID 27873319, 2017). "Consistent with prior discussions, it has been stated that EGFR amplification along with mutation of TERT promoter and 7+/10− are alterations very often present in adult patients with IDH-wild-type GBM, and they can contribute to the upgrade of diffuse or anaplastic astrocytoma to wild-type GBM." (PMID 39057054, 2024). "The group with mutation in IDH but not TERT contained two anaplastic astrocytoma and two GB." (PMID 30076584, 2018).
anaplastic carcinoma (7 papers, 2016 to 2025). "The highest prevalence occurs in anaplastic carcinoma, consistent with the important role of TERT promoter mutation as a marker of disease progression." (PMID 41175860, 2025). "TERT promoter mutations were found in 12 (40 %) of 30 WDTCs with distant metastasis, 2 (29 %) of 7 poorly differentiated carcinomas, and 3 (60 %) of 5 anaplastic carcinomas." (PMID 26857243, 2016). "TERT promoter, PTEN, and PIK3CA gene mutations are rare in adult DTC, while they have been found more frequently in poorly-differentiated carcinomas and anaplastic carcinoma." (PMID 31456750, 2019). "Since MAPK activation in BRAF p.V600E- or RAS-mutated tumors increases TERT transcription, BRAF p.V600E or RAS co-mutation with TERT has been strongly associated with advanced disease and poor outcome, even in aggressive tumors, such as high grade non-anaplastic and anaplastic carcinoma." (PMID 41175860, 2025).